KDM4A (lysine demethylase 4A)
Diseases named in the same sentence as KDM4A in open-access papers (continued):
Sharing a sentence is not in itself a finding about the gene and the disease.
infection (7 papers, 2017 to 2025). The state of being infected such as from the introduction of a foreign agent such as serum, vaccine, antigenic substance or organism. "We found that iPSCs-KDM4A-knockdown (iPSCs-KD) had a lower growth and expansion rate than iPSCs without shKDM4A infection (wild type) (data not shown)." (PMID 41244052, 2025).
prostate (2 papers, 2022 to 2023). "YAP expression can also be induced by ETV1, a member of the ETS protein family, fostering the initiation of prostate malignancy when cooperated with lysine-specific demethylase 4A (KDM4A, also known as JMJD2A)." (PMID 35954292, 2022).
hematological cancer (1 paper, 2021). "In addition, newly developed KDM4A inhibitors efficiently block enzymatic activity and show antitumor activity in solid and hematological cancer cell lines." (PMID 34944554, 2021).
KDM4A also shares sentences with these, for which no sentence is quoted: attention deficit-hyperactivity disorder (2 papers); breast fibroadenoma (2); colitis (2); colorectal adenocarcinoma (2); depression (2); Insulin resistance (2); liver fibrosis (2); neuroblastoma (2); acute lymphoblastic leukemia (1); adenocarcinoma (1); airway allergy (1); cardiovascular diseases (1); colorectal tumors (1); congenital heart disease (1); heart attack (1); immune diseases (1); Infertility (1); infiltrating breast duct carcinoma (1); Kaposi's sarcoma (1); latent infection (1); malignant pleural mesothelioma (1); metastatic tumors (1); migraine (1); pancreatic adenocarcinoma (1); paraganglioma (1); periodontitis (1); pheochromocytoma (1); prostate tumors (1); rhabdomyosarcoma (1); Sepsis (1).
A further 3 diseases each share a sentence with KDM4A in 1 paper.